CD4 (CD4 molecule)
Diseases named in the same sentence as CD4 in open-access papers (continued):
Sharing a sentence is not in itself a finding about the gene and the disease.
Sepsis (continued). "Of note, the high representation of naïve CD4+ T cells was sustainable over 24 h post-sepsis and even transiently higher than that of the sham group at 24 h after CLP, whereas splenic and circulating naïve CD4+ T cells underwent a substantial reduction at 72 h after sepsis." (PMID 35832091, 2022). "Two patients died of sepsis with low CD4 cell counts and high viral loads." (PMID 36547617, 2022). "We further investigated CD4 + T cell survival during sepsis." (PMID 35435531, 2022). "Our results also revealed the role of mTOR in regulating A-L fusion in CD4 + T cells during sepsis." (PMID 35435531, 2022). "This study compared the efficacies of enteral cholecalciferol and/or intravenous (IV) calcitriol administration on mesenteric lymph node (MLN) cluster-of-differentiation-4-positive (CD4+) T cell distribution and intestinal barrier damage in obese mice complicated with sepsis." (PMID 36079813, 2022). "With regard to recombinant cytokines, IL-7 especially is attractive considering its ability to affect many different immune effector cells implicated in pathogen elimination (e.g., CD4 and CD8 T cells, and innate lymphoid cells) and to improve outcome in experimental sepsis." (PMID 36470832, 2022). "Moreover, CD4+CD25+ Tregs significantly increase the early-onset sepsis, aiding in the early diagnosis of sepsis." (PMID 36162982, 2022). "While the Granzyme B expression ratio on CD4+T cells was lower in severe sepsis patients (P=0.026)." (PMID 35898496, 2022). "Finally, we observed an increase in IL-10 secreting by CD4+ T cells in septic patients, which is consistent with prvious published literature on Tregs in sepsis and septic shock." (PMID 36357845, 2022). "Interestingly, the mild sepsis group CD4+T cell had higher expression of T-bet and IFN-γ than severe populations." (PMID 35898496, 2022). "Additionally, septic patients with G- sepsis had a noticeably lower ratio of CD3+CD4+CD69+T/CD3+CD8+CD69+T than that in the G+ sepsis subgroup." (PMID 36703970, 2022). "To confirm that ERS induced apoptosis of CD4+ T cells in sepsis, we first compared the percentage of apoptosis in splenic CD4+ T cells and the expression of the pro-apoptotic gene BIM and expression of the pro-apoptotic protein caspase-3 between WT+SHAM and WT+CLP mice." (PMID 35759162, 2022). "The mTOR pathway influences CD4 + T cell survival during sepsis." (PMID 35435531, 2022). "Therefore, in the present study, we constructed a CLP mouse model of sepsis to explore the dynamics of autophagic flux in CD4 + T cells during sepsis." (PMID 35435531, 2022). "Immunological analysis suggested that 10 cell types (i.e., CD8/CD4 T cells) were lower in sepsis." (PMID 35844488, 2022). "Thus, dynamic monitoring of the level of mHLA-DR is capable of better assessing the immune status and predicting the prognosis of sepsis, further strengthened by its identical tendency with the CD4+ T cell counts." (PMID 35619710, 2022). "In addition, eCIRP can also activate CD4+ T lymphocytes and predispose CD4+ T cells to a Th1 hyperinflammatory response profile and CD8+ T cells to a cytotoxic response profile, thus promoting the inflammatory response in sepsis." (PMID 34953031, 2022). "CD4+ T lymphocytes that survive from sepsis-induced apoptosis reveal anergic profiles, including diminished proliferative capacity, reduced ability to produce effector cytokines, and upregulated expression of various co-inhibitory receptors that inhibit T cell response." (PMID 35619710, 2022). "However, Bax, caspase-3, and BIM were upregulated, the expression levels of Bax, caspase-3, and BIM were upregulated, the BCL-2 expression level was downregulated, and the CD4+ T cell apoptosis rate significantly increased in the lck-TSC1 sepsis mice." (PMID 35915740, 2022). "Patients with sepsis benefit from increased CD4 T lymphocyte count." (PMID 36552302, 2022).
Sepsis (continued). "This could be explained: miR-451a promoted the differentiation of CD4+ T cells into Th1 cells; thus, a positive correlation of miR-451a with Th1 cells in patients with sepsis was shown." (PMID 35992658, 2022). "It is unclear whether IL-9-producing CD4(+) T cells and IL-9 are related to the acute injury of the intestinal mucosal barrier in sepsis." (PMID 33941281, 2021). "Therefore, we analyzed the effect of basil polysaccharide on CD4+ lymphocytes in a mouse model of sepsis-induced secondary S. aureus pneumonia." (PMID 34054345, 2021). "In addition, sepsis has been shown to significantly reduce the proliferation capability of CD4+T cells, thus amplifying the decrease in their number." (PMID 33532141, 2021). "One of the possibilities might be that cell death in CD4 lymphocytes in patients with sepsis was mainly via apoptosis since TLR4 inhibition could elevate the Bcl2 to Bax ratio to suppress apoptosis." (PMID 34733114, 2021). "It was suggested that during the early onset of sepsis, the proliferation of ILCs might be of higher importance than the proliferation of other lymphoid cells, such as CD4 and CD8 T cells, as the latter need more time to orchestrate pathogen defenses." (PMID 33021569, 2021). "Based on the autopsy results of sepsis patients, large quantities of immune cells in the spleen of patients dying of sepsis underwent apoptosis, including CD4+ T cells, CD8+ T cells, B cells, and DCs, which is an important cause of sepsis-related immune paralysis." (PMID 34335278, 2021). "Additionally, CD4+ and CD8+ have reduced TCR diversity post-sepsis episode, which further increases the risk of developing secondary infection." (PMID 34356636, 2021). "Observed that the decrease in miR-150 as a sepsis biomarker was deregulated in the same direction both in whole blood samples and in isolated CD4 T lymphocytes, which shows that specific miRNAs, such as miR-150-5p, are comparable results obtained from whole blood and leukocytes." (PMID 34206682, 2021). "To investigate whether T cells undergo sepsis-induced exhaustion in both AS and RS, we estimated PD-1 and Tim-3 expression, on CD4+ and CD8+ T cell subsets, and the number of Tregs." (PMID 33717146, 2021). "Interestingly, late sepsis activated CD4+ T cells had high expression of ETS1, which has been implicated as a negative regulator of Th17 differentiation." (PMID 34484194, 2021). "In the analysis of healthy controls (n=5) with all sepsis patients day 14-21 (n=4), scRNA-seq revealed differential expression of 11 genes in CD4+, 30 genes in CD8+, 26 genes in activated CD4+, 50 genes in activated CD8+, and 32 genes in regulatory T (Tregs) lymphocytes (adjusted p-value < 0.01)." (PMID 34484194, 2021). "Th1 cell and Th17 cell, differentiated from CD4+ T cells activated by different categories of cytokines, are increasingly indicated to participate in the regulation of infection and inflammation-related diseases, including sepsis." (PMID 33083958, 2021). "In summary, recurrent sepsis exacerbates CD4+ T cell exhaustion and decreases antiviral immune responses, contributing to significant morbidity, increased late mortality, and increased health care burden in recurrent sepsis patients." (PMID 33717146, 2021). "Unlike CD4 and CD8 T cell subsets, Tregs are resistant to sepsis-induced apoptosis and cause further insult to CD4 T cells, inducing their elimination or apoptosis through activation of the transforming growth factor β1 (TGFβ1) signaling pathway." (PMID 34251989, 2021). "Specifically, CD4+ T lymphocytes can show decreased proliferation capacity and improper cytokine responses following sepsis, and a defect in the correct regulation of the TH-specific cytokine pathway can negatively influence inflammatory processes post-sepsis." (PMID 35003073, 2021).
Sepsis (continued). "Specifically, relative to that in normal subjects, the number of BTLA+CD4+ T cells decreased among patients with severe sepsis, and a lower percentage of BTLA+CD4+ T cells during the early stage of sepsis was associated with the severity and mortality of sepsis patients." (PMID 33859648, 2021). "STAT1 and SETD2 are also both over-expressed in late sepsis CD4+ T-lymphocytes." (PMID 34484194, 2021). "In addition, future studies investigating the therapeutic implications of CD4+ T cell exhaustion reversal in order to enhance immune function, reduce secondary infections, and improve long-term survival in recurrent sepsis patients need to be executed." (PMID 33717146, 2021). "In adjunct to biomarkers routinely determined for the prediction of prognosis in sepsis, CD4 T lymphocytes, measured at hospital entry, may be useful in identifying patients at higher risk of in-hospital death." (PMID 34372784, 2021). "GO analysis of the differentially expressed genes illustrated transcriptome involvement of biological processes related to ribosomal function in all T-lymphocyte subsets, except activated CD4+ T cells, further supporting T-lymphocyte exhaustion in late sepsis (adjusted p-value <0.01)." (PMID 34484194, 2021). "Taken together, these data demonstrated that basil polysaccharide could promote naïve CD4+ T lymphocytes to differentiate to Treg cells, thus exerting the immunomodulatory effect in sepsis-induced secondary S. aureus pneumonia mice." (PMID 34054345, 2021). "Numbers of CD4 T cells are greatly reduced following sepsis onset." (PMID 32733454, 2020). "In addition, our data confirmed that CD4+CD25+Tregs appeared to be required for the protection against sepsis elicited by IL‐38." (PMID 31880383, 2020). "Sepsis led to a decrement in CD4+ T-cell percentages in lymph nodes after CLP." (PMID 32290120, 2020). "In contrast to the transient numerical change, the 2W1S-specific memory CD4 T cells displayed prolonged functional impairment after sepsis, evidenced by a reduced recall response (proliferation and effector cytokine production) after restimulation with cognate Ag." (PMID 32903436, 2020). "To gain further insight into T-cell dysfunction induced by replicative senescence of the CD4+/CD8+ T cells in the peripheral blood of lymphopenic patients with sepsis, we performed telomere length measurements of separated CD4+ and CD8+ T cells, applying the T/S method." (PMID 32825352, 2020). "In addition, CD4+ T cells were depleted before sepsis induction to determine the portion of the T cell-dependent and -independent humoral response." (PMID 32425951, 2020). "Targeting metabolism may help to prevent undesirable shifts in CD4 T cell subsets following sepsis, based on recent data showing administration of glutamine led to decreased representation of Th2 and Treg cells in septic hosts." (PMID 32733454, 2020). "Downregulation of the CD4+ T-cell lineage toward Th2 and Th17 may alleviate liver inflammation and subsequent liver damage during sepsis." (PMID 32290120, 2020). "Following recovery from severe sepsis, mice models showed increases in CD4+CD25+Tregs." (PMID 31880383, 2020). "All these effects of IL‐38 were abolished by administration of anti–IL‐38 antibody, therefore providing evidence that IL‐38 could improve the immune activities of CD4+CD25+Tregs in sepsis." (PMID 31880383, 2020). "In addition, CD4+CD25+ Tregs depletion before the onset of sepsis obviously abolished IL‐38–mediated protective response." (PMID 31880383, 2020). "Indeed, depletion of CD4+ T cells before sepsis reduced IgG-production, leaving the IgM-response intact." (PMID 32425951, 2020). "When numerical representation of six different Ag-specific CD4 T cell populations was determined in sham and 1 month post-sepsis mice, half of Ag-specific populations recovered numerically, while one population was found in greater numbers and two were numerically reduced post-sepsis." (PMID 32733454, 2020).
Sepsis (continued). "Moreover, depletion of CD4+ T cells prior to sepsis induction highlighted the fact that both T cell-dependent and T cell-independent components govern the IgG response to sepsis." (PMID 32425951, 2020). "Our data collectively show CLP-induced sepsis results in a transient numerical reduction and long-term functional deficits of Ag-specific memory CD4 T cells, which contributes to the characteristic long-lasting immunoparalysis seen after sepsis and reduced protection to secondary infection." (PMID 32903436, 2020). "We hypothesized that GLN may have favorable effects on regulating CD4+ T cell, alleviating inflammatory response, and subsequent organ injury in obesity complicated with sepsis." (PMID 33223959, 2020). "Intriguingly, we noticed that IL‐38 could markedly improve the immune function of CD4+CD25+Tregs in sepsis." (PMID 31880383, 2020). "Overall, it appears that CD4+ T cells are the subset which are most affected in sepsis patients." (PMID 33336293, 2020). "Sepsis reduces the number of cytokine-producing MOG-specific CD4 T cells in the CNS." (PMID 33191915, 2020). "If targeting changes in CD4 T cell subset representation could provide a therapeutic benefit to sepsis patients, understanding the factors leading to these imbalances becomes important." (PMID 32733454, 2020). "Therefore, understanding how CD4 T cells are impacted by sepsis, including numerical and functional alterations and changes in subset representation, is an important goal in sepsis-based research." (PMID 32733454, 2020). "In summary, the present study showed that sepsis upregulated proBDNF in the immune system, which decreased the meningeal CD4+ T cell infiltration and disrupted the balance of meningeal pro- and anti-inflammatory microenvironments and initiated cognitive dysfunction." (PMID 32466783, 2020). "However, previous work has described how some CD4 T cell precursors eventually recover to pre-sepsis numbers with time, whereas others remain numerically decreased or can even be numerically expanded." (PMID 33191915, 2020). "Additionally, we observed a numerical recovery of MOG-specific CD4 T cells with time after sepsis in some animals." (PMID 33191915, 2020). "Thus, the ratio of NK cells to CD4+ lymphocytes was used to predict the mortality of patients with sepsis." (PMID 32983116, 2020). "Using the cecal ligation and puncture (CLP) mouse model of sepsis, we investigated the impact of sepsis on endogenous Ag-specific memory CD4 T cells generated in C57BL/6 (B6) mice infected with attenuated Listeria monocytogenes (Lm) expressing the I-Ab-restricted 2W1S epitope (Lm-2W)." (PMID 32903436, 2020). "A decrease in CD3 + CD4 + lymphocytes in the peripheral blood in the early stages of the disease in patients with sepsis is noted both in reproductive age and in children aged 1 to 18 years, and the number of T-lymphocytes negatively correlates with the severity of sepsis." (PMID 32985516, 2020). "There was an increase of Foxp3+ Treg cells to all CD4+ T cells during murine sepsis." (PMID 31191818, 2019). "Herein, we aimed to verify the hypothesis that Mdivi-1 protected CD4+ T cells against apoptosis in sepsis." (PMID 31263382, 2019). "During sepsis, Mfn2 expression is increased which could inhibit autophagy and increase apoptosis of CD4+ T cells, thereby suppressing immune function." (PMID 31507440, 2019). "Thus, mucosal and systemic DCs were found to be functionally different in the way CD4 T cells respond during sepsis." (PMID 31323786, 2019). "It would also be important to study their putative regulatory functions in order to determine whether this subpopulation of CD4+ T cells participates in sepsis-induced immune alterations." (PMID 30995946, 2019). "CD4+ naive cells decreased in the two weeks after the onset of sepsis." (PMID 31658288, 2019).
Sepsis (continued). "The increase in CD4 + Foxp3+ and CD8 + Foxp3+ Tregs in vehicle- compared to SBI-425- treated mice is consistent with previous findings which show that elevated Tregs are associated with increased survival and improved sepsis outcomes." (PMID 31827139, 2019). "Based on our results, it is tempting to speculate that the IL-1β upregulated by mucosal DCs may engage in proliferating CD4 T cells during sepsis." (PMID 31323786, 2019). "Therefore, Mdivi-1 treatment as a novel therapeutic strategy targeted apoptosis of CD4+ T cells during sepsis." (PMID 31263382, 2019). "Consequently, it is urgent to develop novel therapeutic strategies to attenuate apoptosis in CD4+ T cells during sepsis to affect the outcome." (PMID 31263382, 2019). "EM CD4+ T cell counts were lower in patients with sepsis than healthy controls (p = 0.011)." (PMID 31658288, 2019). "Thus, our findings suggest a model that sepsis precipitates the formation of a mucosal lymphoid niche favorable for DCs to facilitate CD4 T-cell proliferation and/or activation." (PMID 31323786, 2019). "Sepsis was associated with attenuated CD8+Th1 and CD4+Th17 based lymphocyte response." (PMID 31658288, 2019). "Apoptosis of T lymphocytes is critical in the pathophysiology of sepsis, and CD4+ T cells could directly mediate the host response to sepsis." (PMID 31611560, 2019). "Thus, developing therapeutic strategies to attenuate the apoptosis of CD4+ T cells in sepsis is critical." (PMID 31263382, 2019). "Thus, our study proposes that DCs, depending on their compartments, respond differentially to allogeneic CD4 T cells during sepsis." (PMID 31323786, 2019). "The percentages of CD4+ T cells with naïve phenotypes was lower in patients with infection compared to the control (p<0.001) and sepsis (p<0.001) groups; whereas percentages of EM CD4+ T cells was greater in patients with infection than in the control (p<0.001) and sepsis (p = 0.007) groups." (PMID 31658288, 2019). "Although CD4+ and CD8+ T cells express the IL-7R at similar levels, we found that the beneficial effect of IL-7 treatment on T cell recovery was more pronounced for CD8+ T cells than for CD4+ T cells, which confirms and extends earlier reports on other sepsis models." (PMID 30730978, 2019). "Furthermore, mucosal DCs in sepsis preferentially expressed IL-1β messaging, which has been reported to directly expand CD4 T cells." (PMID 31323786, 2019). "We next tested whether the CD4+ TReg cells increase in early sepsis of our model and might contribute along with CD4+ T cell anergy to immune suppression." (PMID 30069485, 2018). "Randomized controlled trials (RCTS) also found that omega-3 fatty acids could improve CD4 + CD25+ Tregs in the blood of patients with sepsis, which was a marker of improving patient’s immune function." (PMID 29859104, 2018). "Moreover, the encapsulation group induced a more ideal protective efficacy in a MRSA sepsis model by inducing more potent antibody responses and a Th1/Th17 biased CD4+ T cell response when compared with the other two attachment ways." (PMID 35540467, 2018). "Several studies discussed that omega-3 fish oil or omega-3 fatty acids could improve the ratio of CD4 to CD8 in patients with severe sepsis to reduce the mortality." (PMID 29859104, 2018). "However, previous work from our group revealed distinct differences in the ability of individual Ag-specific CD4 T cell populations to numerically and functionally recover after sepsis." (PMID 30429857, 2018). "Thus, it appears that both apoptosis and impairment of cell proliferation contribute to the reduction of CD4 T cell numbers during sepsis." (PMID 30052667, 2018). "We specifically aimed at identifying a myriad of immune cells within a single tissue sample in a specific time frame following CLP-induced sepsis, focusing on the different types of T cells (CD4+ helper T cell, CD8+ cytotoxic T cell, and Tregs), as well as on the different subsets of DCs in the gut." (PMID 30174555, 2018).